IRF1 (interferon regulatory factor 1)
Description:
Transcriptional regulator which displays a remarkable functional diversity in the regulation of cellular responses. Regulates transcription of IFN and IFN-inducible genes, host response to viral and bacterial infections, regulation of many genes expressed during hematopoiesis, inflammation, immune responses and cell proliferation and differentiation, regulation of the cell cycle and induction of growth arrest and programmed cell death following DNA damage. Stimulates both innate and acquired immune responses through the activation of specific target genes and can act as a transcriptional activator and repressor regulating target genes by binding to an interferon-stimulated response element (ISRE) in their promoters. Has an essential role in IFNG-dependent immunity to mycobacteria. Competes with the transcriptional repressor ZBED2 for binding to a common consensus sequence in gene promoters. Represses genes involved in anti-proliferative response, such as BIRC5/survivin, CCNB1, CCNE1, CDK1, CDK2 and CDK4 and in immune response, such as FOXP3, IL4, ANXA2 and TLR4. Plays an important role in immune response directly affecting NK maturation and activity, macrophage production of IL12, Th1 development and maturation of CD8+ T-cells. Also implicated in the differentiation and maturation of dendritic cells and in the suppression of regulatory T (Treg) cells development. Acts as a tumor suppressor and plays a role not only in antagonism of tumor cell growth but also in stimulating an immune response against tumor cells.
Synonyms: IRF-1; MAR; IMD117
Tractability: PROTAC: UniProt records ubiquitination sites on it; ubiquitination databases record sites on it.
Gene: Protein-coding gene on chromosome 5 (132,440,440 to 132,508,719, reverse strand). Ensembl gene ENSG00000125347.
Subcellular location: Nucleus; Cytoplasm
Subcellular location (Human Protein Atlas): Nucleoplasm; Cytosol
Pathways (Reactome):
Immune System: Interferon alpha/beta signaling; Interferon gamma signaling; Regulation of PD-L1(CD274) transcription
Hemostasis: Factors involved in megakaryocyte development and platelet production
Programmed Cell Death: Pyroptosis
Gene Ontology:
Molecular function: DNA-binding transcription activator activity, RNA polymerase II-specific; DNA-binding transcription factor activity; protein binding; RNA polymerase II cis-regulatory region sequence-specific DNA binding; RNA polymerase II transcription regulatory region sequence-specific DNA binding; sequence-specific DNA binding; transcription cis-regulatory region binding; DNA binding; DNA-binding transcription factor activity, RNA polymerase II-specific
Biological process: apoptotic process; cellular response to interferon-beta; cellular response to mechanical stimulus; defense response to virus; negative regulation of DNA-templated transcription; positive regulation of DNA-templated transcription; positive regulation of interferon-beta production; positive regulation of transcription by RNA polymerase II; regulation of cell cycle; regulation of transcription by RNA polymerase II; toll-like receptor 3 signaling pathway; immune system process; negative regulation of cell population proliferation; negative regulation of regulatory T cell differentiation; positive regulation of type I interferon production; regulation of adaptive immune response; regulation of CD8-positive, alpha-beta T cell proliferation; regulation of innate immune response; regulation of MyD88-dependent toll-like receptor signaling pathway; type II interferon-mediated signaling pathway; regulation of DNA-templated transcription
Cellular component: chromatin; nucleus; cytoplasm; cytosol; nucleoplasm
Genetic constraint (gnomAD): Loss-of-function variants: 13 observed, 38.92 expected, observed/expected ratio (o/e) 0.33, 90% interval 0.22 to 0.53. The upper end of that interval is the gene's LOEUF score, 0.53, which puts it in group 2 of 6, group 1 being the genes least tolerant of losing a copy. Missense variants: 230 observed, 406.3 expected, observed/expected ratio (o/e) 0.57, 90% interval 0.51 to 0.63. Synonymous variants: 128 observed, 150.06 expected, observed/expected ratio (o/e) 0.85, 90% interval 0.74 to 0.99.
Homologues: Orthologues: chimpanzee IRF1 (99% identical), macaque IRF1 (99% identical), guinea pig IRF1 (93% identical), dog IRF1 (91% identical), pig IRF1 (90% identical), mouse Irf1 (86% identical), rat Irf1 (86% identical), rabbit IRF1 (83% identical), tropical clawed frog irf1 (53% identical), zebrafish irf1b (41% identical), zebrafish irf1a (28% identical). Paralogues in human: IRF2 (40% identical), IRF4 (24% identical), IRF8 (23% identical), IRF5 (22% identical), IRF6 (20% identical), IRF3 (18% identical), IRF9 (18% identical), IRF7 (17% identical).
Diseases named in the same sentence as IRF1 in open-access papers:
IRF1 is named in the same sentence as 307 diseases in open-access papers, as found by Europe PMC text mining. Sharing a sentence is not in itself a finding about the gene and the disease. The quoted sentences say what the papers report.
viral infection (120 papers, 2009 to 2026). "While RNASET2 like IRF1 is closely linked with immune responses in viral infections and like IRF1 is thought to have a role in cancer, RNASET2 was not identified coregulated with IRF1 in FB2 cells." (PMID 40862725, 2025). "The decreased expression of IRF1 resulting from targeting CARINH with antisense oligonucleotides or genetically in Carinh−/− mice resulted in elevated susceptibility to viral infection." (PMID 39773901, 2025). "Targeted depletion of CARINH or its mouse ortholog Carinh in macrophages reduces the expression of IRF1/Irf1 and their associated target gene networks, increasing susceptibility to viral infection." (PMID 39773901, 2025). "Given the rapid turnover of IRF1 mRNA and IRF1 proteins, XAF1 has more potential than IRF1 to be a sensitive and reliable diagnostic marker of viral infectious diseases." (PMID 35972291, 2022). "There were also some studies that showed that IRF1 knockout mice are more susceptible to viral infections." (PMID 35159296, 2022). "IRF-1 deficient mice show a higher susceptibility to viral infection with different viruses e.g. EMCV, murine γ-herpesvirus 68 or West Nile virus." (PMID 24675692, 2014). "Additionally, RNASET2 like IRF1 is closely linked with immune responses in viral infections and cancer." (PMID 40862725, 2025). "The authors showed that Irf1-deficient mouse EpiLCs were more susceptible to viral infection." (PMID 39195252, 2024). "Loss of Irf1 leads to increased susceptibility to viral infection." (PMID 35852463, 2022). "In support of an important role for IRF1 in viral defense, ectopic expression of IRF1 protects otherwise susceptible cells against a diverse range of RNA viruses, and IRF1 deficient mice are more susceptible to viral infections." (PMID 31156620, 2019). "In human social genomic studies, IRF-1 is usually found to be downregulated in isolated/stressed individuals, and this phenomenon is thought to reflect an adaptive reaction to the low risk of dissemination of a viral infection in isolated individuals." (PMID 25494179, 2014). "An inspection of potential regulatory elements lying close to TSS II reveals clusters of elements for binding heat shock factor I and factors associated with viral infection, such as interferon, IRF-1, NF-kappa B and the element ISRE which binds the IRF transcription factors." (PMID 21062477, 2010). "Thus, it is tempting to speculate that the susceptibility of Irf1-deficient EpiLCs to viral infection is a consequence of immunoproteasome function loss." (PMID 39195252, 2024). "Therefore, we investigated whether IRF1‐mediated ISG expression in EpiLCs influences susceptibility to viral infection." (PMID 35852463, 2022). "STAT1 is translocated to the nucleus and triggers the transcription of interferon-stimulated genes (ISGs), such as Interferon Regulatory Factor-1 (IRF1), which play a key role in the host’s defense against viral infections." (PMID 41596343, 2026). "Taken together, these data identify CARINH and its proximal coding gene IRF1 as a putative cis-acting lncRNA-mRNA pair induced by viral infection in humans." (PMID 39773901, 2025). "Previous studies have shown that IRF1 is induced by a variety of stimuli, including viral infections, with broadly antiviral roles." (PMID 40586041, 2025). "Together, our results suggest a role of CARINH in regulating IRF1 expression and coordinating the expression of ISGs required to limit viral infection in human innate immune cells." (PMID 39773901, 2025). "The basal expression of IRF1 contributes to resistance against multiple viral infections and chronic inflammation." (PMID 40420582, 2025). "Kinetic studies have shown that IRF1 induction by IFNβ is required for the initial amplification of the inflammatory response to viral infection, but that sustained antiviral protection relies on type III IFNs." (PMID 39773901, 2025).
viral infection (continued). "Further in vitro experiments in airway epithelial cell infection models from healthy, asthma, and COPD revealed that IRF1 and HLA-F were rapidly activated within 24 h after viral infection in cells from healthy participants." (PMID 40420582, 2025). "IRF1 is activated in response to viral infections, and its DBD domain recognizes a hexanucleotide unit, “GTGAAA”, referred to as IRF-binding elements, leading to the induction of pro-inflammatory and antiviral immune responses." (PMID 40586041, 2025). "As an IFN-stimulated gene (ISG), both the mRNA transcript and protein of IRF1 are short-lived, allowing the host to exert rapid and dynamic regulation in response to viral infection." (PMID 38589958, 2024). "Various irfs (e.g., irf1, irf2, irf3, irf4b, irf7, irf9, and irf10) were previously found upregulated with poly(I:C) or viral infection in teleost species." (PMID 39211041, 2024). "Upon viral infection, IRF1 translocates to the nucleus, leading to the rapid activation of IFN response." (PMID 38589958, 2024). "Upon viral infection, IRF1 are induced, complexes with BRD4 and both factors load pSer2 Pol II onto target gene promoters." (PMID 38601157, 2024). "Upon virus infection, viral RNA recognizes and binds receptors such as RIG-I and MAD5 and then binds to MAVS in peroxisomes (peroxisome MAVS), leading to the IRF1-dependent production of type III IFNs to counteract viral infection." (PMID 39205283, 2024). "Collectively, these data revealed that TRIM21 restricts viral infection in IRF1-dependent and IRF1-independent manners." (PMID 37327222, 2023). "In the early phase of a virus infection, IRF1 is highly expressed, stimulating the production of IFNs and ISGs." (PMID 36992353, 2023). "IRF1 expression is usually induced rapidly following virus infection and there is evidence that IRF1 effector genes can suppress the replication of a variety of RNA viruses." (PMID 37622112, 2023). "Increases in IRF1 expression induced by viral infections in most cases primarily result from NF-κB and STAT1-mediated transcriptional activation." (PMID 37622112, 2023). "IRF1 is upregulated during viral infection or IFN stimulation, which, in turn, activates transcription of type I IFNs." (PMID 37197656, 2023). "The expression of NOS2 is known to be modulated by IFN-regulatory factor 1 (IRF1); this transcription factor is, indeed, induced by IFNγ during the host immune response to viral infections." (PMID 37893073, 2023). "IRF1, the first identified IRF, has been demonstrated to be implicated in varieties of physical and pathological processes, including viral infection, tumor immunosurveillance, proinflammatory injury, and immune diseases." (PMID 37090158, 2023). "Z-DNA-binding protein 1 (Zbp1) can be induced by type I interferons (IFNs) to upregulate IFN expression after viral infection, thus activating the expression of interferon regulatory factor 1 (IRF1)." (PMID 36851724, 2023). "Mammalian IRF1 is upregulated by viral stimulation and resists viral infection by regulating IFNs and ISGs." (PMID 35379320, 2022). "Interferon regulatory factor 1 (IRF1) is involved in a series of pathophysiological processes in viral infection, tumor immune surveillance, and proinflammatory injury." (PMID 35187081, 2022). "Both IRF1 mRNA and the IRF1 protein are short-lived, allowing for rapid and dynamic regulation during viral infection." (PMID 35972291, 2022). "To investigate how XAF1 facilitates the induction of IRF1 target genes, we first measured the IRF1 expression during viral infection." (PMID 35972291, 2022). "Some key cytokines and ISGs that resist viral infection are also significantly upregulated, showing the same expression trend as IRF1." (PMID 35379320, 2022). "We show that elevating expression levels of IRF1 lead to the sensitization towards cell death across different genotoxic insults, such as chemotherapeutics, γ-IR or cytosolic dsRNA (i.e. virus infection)." (PMID 35436994, 2022).
viral infection (continued). "After a viral infection, IRF1, which is significantly upregulated and expressed in cells, inhibits virus replication by regulating the production of IFN." (PMID 35379320, 2022). "In recent years, IRF1 has been shown to mediate inducible and constitutive host defenses against virus infection, such as Sendai virus, dengue virus, and hepatitis A virus." (PMID 36733771, 2022). "As described by IRF1 promotes the innate immune response to viral infection and exhibits antiviral activity both in DNA and RNA virus infection." (PMID 36016774, 2022). "We conclude that intrinsic upregulation of IRF1 is one of the defense mechanisms of EpiLCs against viral infections." (PMID 35852463, 2022). "Yet, it is also conceivable that upon viral infection Cxcl9+ FRCs represent LNSCs that can acquire anti-viral properties, which was simulated by Irf3 and Irf1 overexpression in the MSC cell line." (PMID 36433946, 2022). "IRF1 not only acts as a viral infection response transcription factor, but also plays a role in cell cycle arrest, enhancing 5-FU sensitivity and suppressing the EMT in gastric cancer." (PMID 35267457, 2022). "The strong protection against viral infection suggests that combined action of the ISGs regulated by IRF1 is required for viral defense." (PMID 35852463, 2022). "ISGs play a major role in defense against viral infection, and IRF1 is a direct regulator of a subset of ISGs." (PMID 35852463, 2022). "Mammalian IRF1 proteins are predominantly localized in the nucleus, allowing more rapid induction of antiviral genes and responses to viral infections." (PMID 35972291, 2022). "A recent study has shown that constitutively nuclear-localized human IRF1 is essential for the basal transcription of antiviral genes required for the defense against multiple viral infection." (PMID 35464458, 2022). "We show here that the formative pluripotency network itself controls the expression of a subset of ISGs through upregulation of IRF1, and thereby protects this stage from viral infection." (PMID 35852463, 2022). "Irf1 therefore acts as a link between the formative pluripotency network, regulation of innate immunity genes, and defense against viral infections during formative pluripotency." (PMID 35852463, 2022). "IRF1 controls constitutive antiviral gene networks to counterattack viral infections in human respiratory epithelial cells, by regulating early expression of IFNs80." (PMID 34753980, 2021). "In the activation of type I ISGs transcription during viral infection, IRF1, -3, -5, and -7 play a pivotal role." (PMID 34445373, 2021). "In most cell types IRF-1 is expressed at a low basal level but is rapidly induced by various stimuli including virus infection, IFN-α/β, and IFN-γ." (PMID 33807175, 2021). "IRF1, through the regulation of autoimmunity, inflammation, viral infections, and innate and adaptive immune responses, is also responsible for the protection of host cells." (PMID 34753991, 2021). "IRF1 is highly upregulated upon viral infections, e.g. in response to influenza virus, RSV and VZV as well as by IFN treatment." (PMID 34248923, 2021). "In conclusion, we here presented– to our knowledge– the first systematic side-by-side comparison of the functional impact of IRF1, -2, -3, -5, -7, and -9 in virus infection, RLR stimulation, and IFN treatment in epithelial cells." (PMID 34685580, 2021). "IRF1 expression in cells can be induced by virus infection and various cytokines as well as other stimuli, such as dsRNA, IFN-α/β, TNF, and IL-1, in different cell types." (PMID 32983049, 2020). "IRF1 mediates both innate and adaptive responses to viral infection such as inducing apoptosis and restricting viral replication." (PMID 33193717, 2020). "In fish, IRF-1 also plays a key role in initiating the induction of clearance-related genes in the apoptotic cells during viral infection." (PMID 32290244, 2020).